ARL8A (ARF like GTPase 8A)
Description:
Plays a role in lysosome motility (By similarity). In neurons, mediates the anterograde axonal long-range transport of presynaptic lysosome-related vesicles required for presynaptic biogenesis and synaptic function (By similarity). May play a role in chromosome segregation (By similarity).
Synonyms: ARL10B; GIE2; FLJ45195
Tractability: Small molecule: a structure with a bound ligand is known. Antibody: its Gene Ontology location is reachable by antibodies, with high confidence. PROTAC: ubiquitination databases record sites on it; its protein half-life has been measured.
Gene: Protein-coding gene on chromosome 1 (202,133,404 to 202,144,743, reverse strand). Ensembl gene ENSG00000143862.
Subcellular location: Late endosome membrane; Lysosome membrane; Cytoplasm, cytoskeleton, spindle; Cell projection, axon; Synapse
Pathways (Reactome):
Immune System: Neutrophil degranulation
Gene Ontology:
Molecular function: GTP binding; protein binding; alpha-tubulin binding; beta-tubulin binding; GTPase activity
Biological process: anterograde axonal transport; chromosome segregation; protein transport
Cellular component: cytoplasm; extracellular exosome; lysosomal membrane; membrane; midbody; spindle midzone; azurophil granule membrane; ficolin-1-rich granule membrane; late endosome membrane; plasma membrane; synapse; axon; axon cytoplasm; spindle
Genetic constraint (gnomAD): Loss-of-function variants: 10 observed, 29.26 expected, observed/expected ratio (o/e) 0.34, 90% interval 0.21 to 0.58. The upper end of that interval is the gene's LOEUF score, 0.58, which puts it in group 2 of 6, group 1 being the genes least tolerant of losing a copy. Missense variants: 129 observed, 221.35 expected, observed/expected ratio (o/e) 0.58, 90% interval 0.5 to 0.68. Synonymous variants: 70 observed, 78.59 expected, observed/expected ratio (o/e) 0.89, 90% interval 0.73 to 1.09.
Homologues: Orthologues: chimpanzee ARL8A (100% identical), dog ARL8A (100% identical), mouse Arl8a (99% identical), rat Arl8a (99% identical), tropical clawed frog arl8a (97% identical), zebrafish arl8a (97% identical), macaque ARL8A (92% identical), Caenorhabditis elegans arl-8 (84% identical), guinea pig ARL8A (78% identical), pig ARL8A (72% identical), rabbit ARL8A (60% identical). Paralogues in human: ARL8B (92% identical), ARL2 (33% identical), ARF1 (32% identical), ARL3 (32% identical), ARL4C (32% identical), ARF3 (32% identical), ARL4D (32% identical), ARL4A (31% identical), ARF6 (31% identical), ARL5B (31% identical), ARL1 (30% identical), ARL13B (30% identical), and 18 more.
Diseases named in the same sentence as ARL8A in open-access papers:
ARL8A is named in the same sentence as 4 diseases in open-access papers, as found by Europe PMC text mining. Sharing a sentence is not in itself a finding about the gene and the disease. The quoted sentences say what the papers report.
colorectal cancer (1 paper, 2018). A primary or metastatic malignant neoplasm that affects the colon or rectum. "Despite the role of ARL8A in colorectal cancer was rarely reported, LMO7 had been manifested dysregulation in human cancers." (PMID 30546056, 2018).
gangliosidosis (1 paper, 2025). A group of autosomal recessive lysosomal storage disorders marked by the accumulation of gangliosides. "In the gangliosidosis models here, in addition to increases in lysosomal proteins, there was increased abundance of proteins involved in lysosomal trafficking including the Arf-like GTPase ARL8a." (PMID 40608809, 2025).
cancer (2 papers, 2018 to 2021). A tumor composed of atypical neoplastic, often pleomorphic cells that invade other tissues. "ARL8A is upregulated in many cancers, including inflammatory BC, and has been associated with poor survival outcomes." (PMID 34298771, 2021).
ARL8A also shares sentences with these, for which no sentence is quoted: tumor (1 paper).